IL15 (interleukin 15)
Diseases named in the same sentence as IL15 in open-access papers (continued):
Sharing a sentence is not in itself a finding about the gene and the disease.
tumor (continued). "We demonstrated that IL-15/IL-15Rα-mediated tumor killing follows distinct kinetics upon CD8+ T cell and NK cell depletion." (PMID 37923822, 2023). "To this end, we included an IL-15 linker portion in our BiKE molecule to promote NK cell growth and function in and around the tumor site." (PMID 37443750, 2023). "After being infused into patients, CAR-NKT cells secreting IL-15 expanded in vivo, effectively infiltrated tumor sites, and mediated tumor regression." (PMID 37596653, 2023). "Among the tested cytokines, IL-15 was the most potent cytokine in stimulating tumor cell killing and expanding both natural killer (NK) cells and CD8+ T cells." (PMID 37923822, 2023). "Nanovesicles derived through extrusion overexpressing the IL-15/IL-15Rα (IL-15/IL-15Rα-NVs) complex boosted the proliferation, activation, and survival of tumor-infiltrated T-cells via the trans presentation of IL-15 to T-cells and the eliminated tumor." (PMID 37345176, 2023). "Morever, the latest research claimed that the CAR T cells modified by IL-15 can be used as double targeting drugs for tumor cells and myeloid-derived suppressor cells in glioblastoma." (PMID 37251333, 2023). "A preclinical study showed great anti-tumor efficacy when mice bearing MC38 colon cancer or ID8 ovarian cancer were treated with IL15-armed vvDD vaccinia virus." (PMID 38002466, 2023). "NK cell dysfunction can also arise from the deprivation of survival signaling from cytokines like IL-15, or as a result of suppressive signals in the tumor microenvironment, such as TGFβ, hypoxia and IDO, which are discussed in detail below." (PMID 36980629, 2023). "We developed a biomimetic nanovaccine (biNV) via the engineering of dendritic cell (DC)-derived cytomembrane vesicles that efficiently delivered IL-15 to tumor-specific T cells for potent and safe cancer immunotherapy." (PMID 37875481, 2023). "We have previously shown that KD033-surrogate, the anti-mouse-PD-L1/IL-15 immunocytokine, was efficacious in several syngeneic murine tumor models including those that were refractory to anti-PD-1/PD-L1 checkpoint blockers." (PMID 36454338, 2023). "In comparison to IL-15, IL-7 promotes the expansion of naïve T cells and leads to a more potent tumor-killing response." (PMID 37064017, 2023). "LH01 not only had a prolonged half-life and improved the tumor-targeting distribution of IL-15, it also overcame resistance to PD-L1 blockade and reduced both CT-26 and MC-38 tumor burden in mouse models." (PMID 36936961, 2023). "In a tumor model, IL‐15/IL‐15Rα NVs–PD‐1/PD‐L1 inhibitor 1 treatment effectively delayed tumor growth and further enhanced the antitumor response, inhibited tumor growth, and improved the survival rate of mice." (PMID 37409429, 2023). "For instance, tumor-resident ILC1s in chromophobe renal cell carcinoma express granzyme A in response to IL-15 derived from cancer cells, and other mouse models have shown granzyme-expressing ILC1s." (PMID 37514187, 2023). "Anti-mPD1-IL15m exhibits more substantial anti-tumor effects than IL-15 super agonists/anti-mPD1/both combinations and is a promising molecule with a better safety profile than IL-15 super agonists." (PMID 37251333, 2023). "The resulting tumor spheroids were co-cultured with PBLs, showing tumor cell killing when IL-15/IL-15Rα was produced by the tumor cells." (PMID 37923822, 2023). "After differentiated for 6 days, P-CIML-NK (PBMCs were primed with IL-12, IL-15, and IL-18) and P–c-NK (PBMCs were primed with low concentration IL-15) cocultured with tumor targets for 6 h and then detected by flow cytometer." (PMID 36932395, 2023). "For example, the first tumour-targeting recombinant IL-15, Bj-001 injection, was initially indicated to be effective against advanced/metastatic solid tumours and was therefore further evaluated in clinical trials (NCT04294576)." (PMID 37076492, 2023).
tumor (continued). "The scavenger receptor type I class B receptor (SR-B1) expressed on the surface of tumor cells is a receptor for ApoA-I and this allows SR-B1 to aggregate chimeric proteins on the surface of tumor cells to deliver IL-15 to NK and CD8+ T cells." (PMID 36936961, 2023). "Expression of cytolytic, and immunomodulatory transgenes-IL-15 introduction is performed to mediate tumor cell lysis which further decreases tumor size and induces innate and adaptive effector immune responses." (PMID 37006286, 2023). "IL-15 agonists have demonstrated significant inhibition of tumor growth and anti-metastatic properties in preclinical studies and are currently undergoing clinical investigation." (PMID 37251333, 2023). "We used TPA to target the delivery of cytokine‐encoding transgenes for interleukin‐12 (IL12), and novel isoforms of IL15 and tumour necrosis factor alpha (TNFα) for tumour immunotherapy." (PMID 35758207, 2022). "Further studies reveal that oncolytic Ad5-Ki67/IL-15 effectively reduces neovascularization in GA-MSCs, indicating potential anti-tumor angiogenic capacity." (PMID 35765095, 2022). "GPC3-CAR co-expressing IL-21 and IL-15 have demonstrated superior in vitro and in vivo expansion, persistence and anti-tumour activity." (PMID 35158772, 2022). "CAR-T cells overexpressing IL-15 alone demonstrated enhanced viability, retarded exhaustion in vitro and superior tumor-inhibitory effects in vivo." (PMID 36167591, 2022). "This study indicates a potential new approach for GBM treatment using Ad5-Ki67/IL-15 to target not only tumor cells but also MSCs." (PMID 35765095, 2022). "Early studies showed that recombinant single chain IL-15 (rhIL-15) produced in Escherichia coli has substantial anti-tumor activity." (PMID 36713398, 2022). "T cells survival in tumor tissue is vital to sustain an anti-tumor response, which relies on the interleukin 15 pathway and interleukin 2 pathway." (PMID 35264912, 2022). "IL-15 was found to significantly augment the magnitude and duration of the anti-tumor response in the EL4-hCD20 syngeneic model treated with Rituximab and the ALT MET-1 xenograft model treated with Alemtuzumab." (PMID 36300122, 2022). "IL-15’s anti-tumour response is well documented and The American National Cancer Institute identified it as one of the most promising cancer immunotherapy targets." (PMID 35020761, 2022). "After coculture with IL-15 and IL-2 for 7 days, the cell viabilities were measured for each type of tumor based on LDH method." (PMID 36213822, 2022). "A seminal study has demonstrated that allogeneic NK cells engineered to express a CAR and IL-15 have encouraging anti-tumor activity in lymphoid malignancies, but obstacles still remain for scalability, activity in solid tumors, and reliable persistence." (PMID 35720306, 2022). "In the three cancer types, patients with lower IL-15 expression were with higher-level tumor status." (PMID 36467072, 2022). "Clinical trials combining NK cell therapy and IL-15 cytokine support resulted in limited anti-tumor responses in patients due to a short half-life after delivery." (PMID 35720306, 2022). "As for K562 cells, HODHBt alone did not increase NK cells’ cytotoxicity, but it did enhance the ability of IL-15-treated NK cells to kill both tumor cell lines." (PMID 35867565, 2022). "Many studies suggested that IL-15 is involved in tumor suppression by enhancing anti-tumor immunity." (PMID 36467072, 2022). "This process is mediated by IL-15, but the study adds a central aspect of exercise immunology in the context of tumor diseases." (PMID 35995771, 2022). "The 2B4/CD3ζ/soluble interleukin-15 (sIL-15) CAR-NK cells show comparable tumor control against CD123+ MV-4-11 cells in vivo to 2B4/CD3ζ CAR-NK while displaying an exponential increase in the circulating cell count (35 days; n=5-7)." (PMID 36445164, 2022). "This provides a new strategy that inhibited tumor angiogenesis to treat GBM using Ad5-Ki67/IL-15 targeting GA-MSCs in future." (PMID 35765095, 2022).
tumor (continued). "It was also reported that the demethylation of FCER1G was induced by IL15 in the NKp30 + CD8+ T cells population exhibiting high natural killer-like anti-tumor potential." (PMID 35711924, 2022). "Encouragingly, in a mouse model of KG-1 AML, NKG2D CAR/IL15-NK treatment significantly prolonged the survival of mice and even achieved complete tumor regression after multiple injections." (PMID 36428748, 2022). "To this aim, we isolated TILs from MC38‐derived tumor masses grown in control or Drp1‐cKO mice (treated with anti‐IgG or anti‐PD‐1) and let them expand in vitro in the presence of IL‐2, IL‐7 and IL‐15 cytokines." (PMID 34535949, 2022). "IL-15 expression was negatively correlated to tumor stage in LUAD, COAD, READ, COADREAD, ESCA and SKCM." (PMID 36467072, 2022). "Another approach employed by two groups used an IL-15 receptor fusion construct comprising of an IL-15 superagonist and IL-15 receptor α (IL-15SA/IL-15RA) to increase anti-tumor activity of PB-NK and iPSC-NK cells, respectively, in vitro and in vivo." (PMID 35185932, 2022). "Going a step beyond, CD19 CAR-NK cells have been engineered to express IL-15/IL-15 receptor α (IL-15/IL-15Rα) fusion protein, endowing them with enhanced persistence regarding their IL-15 secreting counterpart and potentially sustaining tumor control." (PMID 35990652, 2022). "In the next set of experiments, since TCR interaction with tumor HLA is required, IL-15 activation was used." (PMID 35965544, 2022). "Here, we report that EVs derived from human NK-92 cells stimulated with IL-15 + IL-21 show enhanced cytotoxic capacity against tumor cells." (PMID 34316033, 2022). "CISH is a key negative regulator of IL-15 signaling in NK cells, and it plays a key role in the regulation of human NK cell metabolic activity and thereby modulates anti-tumor activity." (PMID 36601109, 2022). "Briefly, αβTCR- and CD56-depleted PBMC stimulation with known-in-the-art T cell stimulators, anti-CD3 mAb (clone: OKT-3) and IL-15, leads to robust Vδ1 cell expansion of high purity and innate-like anti-tumor efficacy." (PMID 35711450, 2022). "On the other hand, ILC1s are activated through an array of cytokines such as IL-15 from tumour cells in CRC, IL-12 or IL-18 from other immune cells." (PMID 35557940, 2022). "Evidence supports that IL-15 preserves stemness and induces higher anti-tumor activity and proliferation via mTOR inhibition." (PMID 36358860, 2022). "Upon the recognition of tumor antigens, myeloid cells, especially dendritic cells (DCs) and macrophages produce inflammatory cytokines such as type-1 IFNs, IL-12, IL-15, IL-18, IL-21 involved in the natural killer (NK) cell tumor-killing response." (PMID 36341428, 2022). "The levels of CXCL13, ICAM-1, MCP-5, and IL-7 in the serum, and the levels of IL-15 and sFasL in the tumor tissue decreased significantly after rAd-mIL-28B treatment relative to rAd-EGFP." (PMID 35935577, 2022). "We next investigated the potential role of CD8+ T cells in the reduced rate of tumor growth in NSG‐Tg(hu‐IL15) mice." (PMID 35959876, 2022). "From a clinical perspective, a better understanding of innate lymphocytes and tumor-derived cytokines, such as IL-15, is key to establish more effective cancer immunotherapies." (PMID 36115839, 2022). "This was also reflected by a decrease in anti-tumor activity of the recombinant L. monocytogenes when rBCG::IL-15 was administered." (PMID 35632582, 2022). "The initial serum concentrations of IL-5, IL-6, IL-8, and IL-15 in the normal control group were significantly lower than those in the tumor patients, and the difference was statistically significant (P < 0.05)." (PMID 36105450, 2022). "The trispecific Killer cell engager (TRiKE) format also exists, in which 2 tumor antigens are targeted along with CD16a, even if others add IL-15 in place of the third scFv." (PMID 35720368, 2022).
tumor (continued). "That being said, the cytotoxicity of patient-derived γδT cells against target tumor cell SH-SY5Y was definitely enhanced in the presence of IL-15 only, compared to those cultured in IL-2 only." (PMID 35351861, 2022). "Ultimately designed to induce a durable tumor antigen-specific immune response, PD-L silenced IL-15 DCs were capable of surpassing PD-1-mediated inhibition by antigen-specific T cells." (PMID 35250967, 2022). "Although considered mainly as producers of cytokines, it has been shown that CD56bright NK cells are able to perform cytotoxic function, specifically after activation by IL-15, against tumor cells in vitro and in vivo." (PMID 36300122, 2022). "Exposure to IL-15 and possibly other contact signals directly presented by the tumor favors acquisition of cytotoxic molecules and ILC1 differentiation towards tumor-killing ieILC1s or ILC1ls." (PMID 36372017, 2022). "IL-15 is a cytokine of great interest to the cancer immunotherapy field; it enhances anti-tumor responses through the stimulation of several leukocyte populations, including cytotoxic CD8+ T lymphocytes and NK (Natural Killer) cells." (PMID 36713398, 2022). "Our previous work demonstrated that Ad5-Ki67/IL-15 selectively killed tumor cells and exhibited potent antiangiogenic capacity via reduction of VEGF secretion." (PMID 35765095, 2022). "IL-15 immunomodulatory properties are being explored alone or in combination with other agents to potentiate anti-tumor responses." (PMID 35493522, 2022). "In vivo studies revealed that CISH-/- iC9/CAR19/IL-15 CB-NK cells persisted twice as long as control CAR19/IL-15 NK cells and significantly improved anti-tumor responses since animal treated with CISH KO iC9/CAR19/IL-15 CB-NK cells were tumor free." (PMID 35493522, 2022). "Similar proportions of CD56dim/CD16+ NK cells isolated from the tumor microenvironment of NSG‐Tg(Hu‐IL15) mice express functional markers CD69, CD8, and NKG2D, and produce granzyme A and granzyme B when compared to NSG mice." (PMID 35959876, 2022). "Another area of study is cellular immunotherapy with natural killer cells stimulated with an IL-15 analog or CD4/CD8 cells stimulated with tumor neoantigens." (PMID 36844955, 2022). "The CD16A can also enhance the interleukin-2 (IL-2) and interleukin-15 (IL-15)-driven NK cell proliferation and cytotoxicity against tumor cells." (PMID 36359863, 2022). "In the SCID lymphoma human xenograft model, the iC9/CAR.19/IL-15 T cells demonstrated greater effectiveness, along with better persistence and anti-tumor effects." (PMID 35806311, 2022). "This approach successfully enhances NK cells’ in vitro and in vivo anti-tumor activity, persistence and metabolic fitness by increasing the sensitivity to IL-15." (PMID 36445164, 2022). "injected luciferase-expressing SKOV-3 tumor cells in NSG mice before transferring NK cells primed overnight with IL-15 +/- CHIR99021." (PMID 36569860, 2022). "As IL-12/15/18-activated NK cells have shown potent anti-tumor activities against a wide range of tumors, this motivated us to compare the effect of EVs derived from resting (cultured in IL-15 alone) versus IL-12/15/18-activated NK cells." (PMID 35119498, 2022). "Skeletal muscle can secrete cytokines such as IL-6, IL-8, and IL-15 in an autocrine, paracrine, or endocrine manner, which promotes systemic inflammation and subsequently tumor growth." (PMID 35241010, 2022). "The development of functional NK cells within HSC‐engrafted NSG‐Tg(Hu‐IL15) mice creates a platform within immuno‐oncology for the in vivo study of NK cells in tumor–immune system interactions and testing novel immunotherapies mediated by NK cells." (PMID 35959876, 2022). "Structurally similar to interleukin 2 (IL-2), IL-15 supports the persistence of CD8+ memory T cells while inhibiting IL-2-induced T cell death that better maintains long-term anti-tumor immunity." (PMID 35806311, 2022).
tumor (continued). "As this reductionist system perfectly allows to integrate other signals regulating inhibitory receptor expression we included tumor‐microenvironment associated cytokines TGF‐β and IL‐15 in our culture system." (PMID 34716584, 2022). "IL-15 transgenic overexpression in the same PyMT models also further expanded TCR−NK1.1 + CD49ahi ILC1-like cells around tumour areas." (PMID 35557940, 2022). "In vivo, they also tested the continue reexposure of GD2.CAR to tumor cells and the results further highlighted the role of IL-15 to promote superior survival of CAR-T cells with greater antitumor activity." (PMID 36172343, 2022). "Incorporating IL-15 by itself or together with its IL-15 receptor complex into a CAR design both significantly improved anti-tumor effects on treating various tumors and potentiated T/NK persistence." (PMID 35806311, 2022). "The interleukin IL-15 emerged as an immunomodulatory cytokine with anti-tumor effects thanks to its roles in inducing expansion and activation of NK, natural killer T (NKT) cells, and long-lasting memory CD8+ T cells (CTLs)." (PMID 35211124, 2022). "The local delivery of mRNAs encoding interleukin-12 (IL-12) single chain, interferon-α, granulocyte-macrophage colony-stimulating factor, or IL-15 sushi led to robust anti-tumor immune responses and tumor regression in multiple murine models." (PMID 35747139, 2022). "In different tumor-bearing animal models, IL-15 treatment contributes to tumor regression, reduction of tumor metastasis, and improvement of animal survival." (PMID 36466812, 2022). "They utilized an IL15Rα-IL15-encoding OV as the T-cell activating stimulus and a prostaglandin synthesis inhibitor as the anti-immunosuppressant, together with ACT of tumor-specific T cells." (PMID 36221123, 2022). "When combined with checkpoint inhibition, OMCPmutIL-2 substantially improved survival of mice that received concomitant anti–CTLA-4, resulting in tumor regression in 3 out of 5 mice, while PD-1 blockade potentiated IL-15–based immunotherapy." (PMID 35603788, 2022). "This suggests that IL15 is preferentially produced at tumor sites at which CD123-ENG.IL15 T-cells are activated by CD123-positive AML blasts (BM or spleen)." (PMID 35615350, 2022). "This dual function of Doxorubicin helps the immune system to mount effective anti-tumor responses and provides the rationale for combining doxorubicin with IL-15." (PMID 36713398, 2022). "The most essential cytokines in the anti-tumour response are IL-12, granulocyte-macrophage colony-stimulating factor GM-CSF, T cell growth factor IL-2, IL-2-related cytokines IL-15 and IL-21 and pro-inflammatory IFNγ and TNFα." (PMID 36140243, 2022). "Preclinical data for co-expression of CAR with IL-15 in NK cells showed long-term persistence and improved anti-tumor activity compared to exogenous IL-15 administration in a CAR-only in vivo model." (PMID 36348457, 2022). "IL-15 plays an essential role in NK cell development, promoting survival and enhancing NK cell mediated anti-tumour responses." (PMID 36505400, 2022). "Since its discovery in 1944, researchers have investigated methods to utilize IL-15’s immunomodulatory abilities to promote anti-tumor responses against cancers." (PMID 35806311, 2022). "IL-15 enhances anti-tumor responses of murine and human CD8+ T cells and NK cells, and is considered a promising agent for cancer immunotherapy." (PMID 36032129, 2022). "They bind to specific antigens on the tumor cell surface; secrete the cytokines IL-12, IL-15, and IL-18; and then recognize and eliminate tumor cells." (PMID 35410257, 2022). "IL-15 also induced increased killing in ZOL or BrHPP-activated Vδ2 T cells against different tumor cell lines (Daudi and U299 cells) compared to IL-2 alone." (PMID 36429001, 2022). "We first tested TPA at 5 × 1010 TU/mouse and found a significant expression of IL15 mRNA by RGD4C.TPA.IL15IgK in tumours." (PMID 35758207, 2022).